FGF23 (fibroblast growth factor 23)
Diseases named in the same sentence as FGF23 in open-access papers (continued):
Sharing a sentence is not in itself a finding about the gene and the disease.
hypophosphatemia (continued). "The therapy to be used for these forms is different from that used for FGF23-dependent hypophosphatemia." (PMID 39377903, 2025). "Hypocalcemia induces an increase in PTH, which leads to phosphaturia and prolongs hypophosphatemia after the FGF23 increase has returned to normal." (PMID 40636514, 2025). "The 3 patients in the “TIO group” were all males, presenting with hypophosphatemia with inappropriately elevated intact FGF23 levels and high alkaline phosphatase activity." (PMID 39963340, 2025). "More investigations are needed, ideally as part of a clinical trial, in order to determine the potential utility of burosumab for the treatment of FGF23-mediated hypophosphatemia in patients with FD." (PMID 40297189, 2025). "The spontaneous remission of FGF23-related hypophosphatemia after admission was similar to that observed in previous patients with alcoholic osteomalacia and was reversible by alcohol abstinence." (PMID 39963340, 2025). "Treatment with the anti-FGF23 antibody burosumab, approved for treating X-linked hypophosphatemia, has alternatively been described in HRAS-associated hypophosphatemia." (PMID 40611284, 2025). "Among the whole cohort, the only additional patient with hypophosphatemia had normal serum FGF23, αKlotho and PTH levels but hypovitaminosis D (11.8 ng/mL)." (PMID 40133996, 2025). "Considering the causes of hypophosphatemia, numerous reports, both in vitro and in vivo, have demonstrated RAS activation-induced FGF23 elevation." (PMID 40611284, 2025). "A new alternative treatment for FGF-23-mediated hypophosphatemia is the antibody burosumab, which is outside the scope of this review." (PMID 41146174, 2025). "FGF23 elevation with ensuing hypophosphatemia has been posited to possibly ameliorate arterial calcification in patients with GACI." (PMID 41445557, 2025). "The impaired bone metabolism in TIO is due to FGF23-induced hypophosphatemia resulting from renal phosphate wasting as well as decreased intestinal phosphate absorption through decreased 1,25-dihydroxy vitamin D production." (PMID 40922882, 2025). "FGF23 excess results in renal phosphate wasting and impaired synthesis of 1,25-dihydroxyvitamin D (1,25(OH)2D), consecutive hypophosphatemia, and eventually in rickets and osteomalacia." (PMID 40295317, 2025). "In our patient, tertiary hyperparathyroidism was observed in the course of long-standing secondary hyperparathyroidism due to FD-related FGF23-mediated hypophosphatemia." (PMID 40357201, 2025). "Bone fractures, limb deformities, and rickets/osteomalacia represent the consequences of a disrupted phosphorus homeostasis (FGF23-induced hypophosphatemia) and RAS-mediated malformations of bone development." (PMID 41008628, 2025). "This case demonstrates how ferric carboxymaltose can precipitate profound and persistent hypophosphatemia through FGF-23-mediated phosphate wasting, even in a patient with long-standing nutritional support and stable TPN." (PMID 41362568, 2025). "Among the acquired forms of FGF23-dependent hypophosphatemia, there is tumor-induced osteomalacia (TIO), a rare paraneoplastic condition characterized by bone demineralization and a loss of phosphate through the kidney." (PMID 39377903, 2025). "Although a previous report from our department focused on the phenomenon in which FGF23-related hypophosphatemia turned on and off depending on the alcohol drinking status of the patients, the source of excess FGF23 secretion remained uncertain." (PMID 39963340, 2025). "“7H syndrome” would describe the syndrome of high FGF23, hypercalcemia, hyperphosphaturia, hypophosphatemia, hypovitaminosis D, hypocalcemia, and secondary hyperparathyroidism." (PMID 41445551, 2025). "Osteoglophonic Dysplasia (OGD) is an autosomal dominant skeletal dysplasia characterized by impaired bone growth resulting in short stature, severe craniofacial abnormalities, and in some patients FGF23-mediated hypophosphatemia." (PMID 41473314, 2025).
hypophosphatemia (continued). "The mechanism of hypophosphatemia following parenteral iron administration is well-described via a disruption of FGF-23-mediated phosphate homeostasis, resulting in increased urinary phosphate excretion." (PMID 41445550, 2025). "Literature suggests that octreotide, a somatostatin analog, can inhibit FGF23 secretion, thereby improving hypophosphatemia and bone abnormalities." (PMID 39866529, 2025). "The confirmation that FD cells were the source of elevated levels of the phosphaturic hormone FGF23 leading to hypophosphatemia, also led to the discovery that normal bone cells are the physiologic source of FGF23." (PMID 40781626, 2025). "The development of hypophosphatemia with ferric carboxymaltose is mediated by the upregulation of fibroblast growth factor 23 (FGF23), which is a phosphaturic hormone produced by osteocytes and a regulator of phosphate homeostasis." (PMID 40725553, 2025). "Hypophosphatemia and an inappropriate increase in FGF23 levels recurred after the patient resumed drinking, which confirmed the diagnosis of alcoholic osteomalacia." (PMID 39963340, 2025). "In patients with chronic overproduction of FGF-23, renal phosphate wasting and hypophosphatemia are characteristic." (PMID 41583152, 2025). "To clarify, XLH is caused by a loss-of-function mutation in the phosphate-regulating endopeptidase homolog X-linked (PHEX) gene, which normally regulates FGF-23 production, leading to uncontrolled FGF-23 production and hypophosphatemia." (PMID 41583152, 2025). "PMTs are rare FN1-fusion-associated neoplasms of uncertain histogenesis and typically induce osteomalacia and hypophosphatemia due to FGFR1 induced secretion of Fibroblast growth factor 23 (FGF23)." (PMID 39404883, 2025). "Blood tests showed hypophosphatemia and elevated serum alkaline phosphatase and FGF23 levels and CT and bone scintigraphy showed multiple bone fractures." (PMID 39866919, 2025). "A phase II, open-label study, Burosumab for Fibroblast Growth Factor-23 Mediated Hypophosphatemia in Fibrous Dysplasia (NCT05509595), is currently ongoing for adult and pediatric patients." (PMID 40538772, 2025). "Under these conditions, FGF23-related hypophosphatemia was confirmed (Pi, 1.5 mg/dL; iFGF23, 113 pg/mL)." (PMID 39963340, 2025). "Loss of function variants of SLC34A1 result in decreased phosphate reabsorption in the renal tubule with resulting hypophosphatemia which decreases FGF23." (PMID 40765620, 2025). "In contrast, when FGF23 is oversecreted from mature osteocytes (eg, in patients with congenital FGF23-related hypophosphatemia), the FGF23 expression level in the bone should be elevated." (PMID 39963340, 2025). "Treatment of frank hypophosphatemia has been traditionally similar to other disorders of FGF23 excess and includes oral phosphate supplements and calcitriol or alphacalcidol." (PMID 40297189, 2025). "This case is a rare instance of persistent FGF23-mediated hypophosphatemia resulting in osteomalacia owing to the unusually frequent fortnightly infusions of intravenous ferric carboxymaltose." (PMID 41445556, 2025). "Consistent with FGF23-related hypophosphatemia, the urinary excretion of phosphate was high (tubular maximum for phosphate reabsorption per glomerular filtration rate [TmP/GFR]: 1.2 mg/dL)." (PMID 39963340, 2025). "Given the significant hypophosphatemia in the presence of a pleural mass, the suspicion of oncogenic osteomalacia was raised, prompting a request for the FGF-23 level." (PMID 39803160, 2024). "In summary, this translational study provides possible evidence of hepatic FGF23 excessive secretion in the setting of acute hepatitis contributing to severe hypophosphatemia." (PMID 39525686, 2024). "Some FGF23 hyperfunction disorders leading to hypophosphatemia have been identified in which rickets/osteomalacia is a main clinical manifestation." (PMID 37991698, 2024).
hypophosphatemia (continued). "Overexpression of FGF23 leads to excessive phosphate consumption, hypophosphatemia, reduced vitamin D levels, and decreased BMD." (PMID 38902808, 2024). "Its primary pathological mechanism stems from the tumor's unchecked production of FGF23, leading to chronic hypophosphatemia and reduced bone mineralization." (PMID 39185431, 2024). "In both patients, there was a resolution of hypophosphatemia and normalization of FGF23 levels after tumor excision, similarly to our case." (PMID 38806758, 2024). "We report here two clinical cases with profound hypophosphatemia revealing major hepatic FGF23 overexpression in the context of acute hepatitis, as confirmed by serum biochemistry and liver biopsy as well as experimental murine models." (PMID 39525686, 2024). "Although both Scl34a1−/− mice and Fgf23−/−Scl34a1−/− mice showed hypophosphatemia and hypercalcemia, the marked increase of osteoid was observed in Fgf23−/−Scl34a1−/− mice but not in Scl34a1−/− mice." (PMID 38396954, 2024). "A very high FGF23 level confirmed FGF23-mediated hypophosphatemia, suggesting a likely diagnosis of TIO." (PMID 39464221, 2024). "In this study, we found that ablation of Cyp24a1 increased fetal calcitriol, which was accompanied by hypercalcemia, modest hypophosphatemia, increased FGF23, and normal skeletal development and mineralization." (PMID 38577520, 2024). "Increased FGF-23 reduces renal phosphate reabsorption, leading to hypophosphatemia and decreased 1,25-dihydroxyvitamin D synthesis." (PMID 39857606, 2024). "Strikingly, these mice also displayed increased serum levels of total and intact FGF23 and hypophosphatemia." (PMID 38530370, 2024). "This induced tumor remission with subsequent normalization of his FGF23 levels and hypophosphatemia." (PMID 38817847, 2024). "Burosumab is a potential therapeutic option to manage hypophosphatemia related to FGF23 in patients with CSHS." (PMID 39416269, 2024). "A contemporaneous report by Lorenz-Depiereux described seven patients, five of whom had intact plasma FGF23 at either the upper range of normal or slightly elevated upon repeated measurement and in any case inappropriate for the hypophosphatemia." (PMID 37871131, 2024). "In contrast, uncontrolled FGF23 production by mesenchymal tumor can induce major renal phosphate waste with hypophosphatemia, responsible for oncogenic osteomalacia." (PMID 39525686, 2024). "Our patient's prolonged hypophosphatemia subsequent to FCM administration was predominantlydriven by “inappropriately normal FGF23” activity." (PMID 38746049, 2024). "It is also suggested that FCM promotes secondary hepatic and lymphatic iFGF23 production without corresponding cleavage, leading to elevated circulating active FGF23 and further worsening hypophosphatemia." (PMID 39703298, 2024). "Further complementary studies are also necessary to explore the clinical relevance, frequency and prognostic influence of FGF23-induced hypophosphatemia in acute hepatitis." (PMID 39525686, 2024). "According to data from the Cooperative European Pediatric Renal Transplant Initiative (CERTAIN) registry, more than one-in-ten patients had hypophosphatemia 12 months after KTx, correlated with FGF23 levels." (PMID 39384649, 2024). "This led to the conclusion that the hypophosphatemia was secondary to fibroblast growth factor 23 (FGF-23) abnormalities." (PMID 39506984, 2024). "The overproduction of FGF23 culminates in severe renal phosphate wasting, leading to hypophosphatemia." (PMID 39464221, 2024). "Abnormal levels of FGF23, a factor secreted by osteoblasts and osteocytes, have been observed in metabolic disorders such as hypophosphatemia and rickets." (PMID 39066929, 2024). "These mice are characterized by renal Pi wasting consequently leading to hypophosphatemia, hypoparathyroidism, reduced FGF23 levels and hypercalcemia." (PMID 39043847, 2024).
hypophosphatemia (continued). "In the case of PMT, the resulting hypophosphatemia is due to high levels of fibroblast growth factor-23 (FGF23), a hormone that blocks the synthesis of 1,25-dihydroxycholecalciferol by inhibiting 1-α-hydroxylase and increasing renal phosphate excretion." (PMID 39493128, 2024). "These drugs are known to elevate fibroblast growth factor 23 levels, resulting in hypophosphatemia, but in past reports, hypophosphatemia attributable to SFO treatment has been associated mainly with prolonged administration over several weeks." (PMID 38584682, 2024). "The evaluation revealed severe hypophosphatemia, an inappropriately normal fibroblast growth factor 23 C-terminal (cFGF-23) level, and a 30 x 20 mm hypermetabolic right pleural mass, which was subsequently proven to be EHE." (PMID 39803160, 2024). "Excessive FGF-23 levels can reduce phosphorus reabsorption in the renal tubules and increase phosphorus excretion in the urine, leading to hypophosphatemia." (PMID 39749027, 2024). "Treatment with Burosomab, an FGF23 antibody, is now an approved therapy for X-linked hypophosphatemic rickets and inoperable TIO, to tackle persistent hypophosphatemia due to a primary increase in FGF23 production." (PMID 38731904, 2024). "Hypophosphatemia, elevated serum FGF‐23, low 1,25 (OH)2D, and decreased percentage of tubular reabsorption of phosphate." (PMID 38887173, 2024). "Each patient presented with inappropriate elevation of FGF23 levels (>30 pg/mL) with concomitant hypophosphatemia." (PMID 39498416, 2024). "Differential diagnoses of FGF23-mediated hypophosphatemia have been established, but the ideal clinical management of CSHS patients is still unclear." (PMID 39416269, 2024). "Biochemical evaluation revealed severe hypophosphatemia due to low renal tubular reabsorption of phosphate with raised intact FGF23 values." (PMID 37436671, 2023). "Bone HRASG12V mice demonstrated a nearly 50-fold increase of blood-intact FGF23 levels that resulted in hypophosphatemia and hyperphosphaturia." (PMID 36943390, 2023). "Mutations in PHEX, DMP1, and FAM20C have been reported to be responsible for FGF23-related hypophosphatemia." (PMID 36776964, 2023). "Following KT, high PTH and FGF-23 levels increase urinary phosphate excretion and result in hypophosphatemia as the graft function recovers." (PMID 37183797, 2023). "In contrast with the administration of anti-FGF23 antibodies in younger mice, and despite the full correction of hypophosphatemia, 12-week-old Dmp1-null mice showed only a partial rescue of bone growth and mineralization." (PMID 37943605, 2023). "The combination of hypophosphatemia in children and adults and intact FGF23 concentrations greater than 30 pg/mL allows for the identification of patients with FGF23-mediated disorders." (PMID 37047636, 2023). "Her laboratory data showed hypophosphatemia and increased fibroblast growth factor 23 (FGF-23) together with reduced bone mineral density on bone densitometry." (PMID 37304318, 2023). "Tumor-induced osteomalacia (TIO) is a rare acquired paraneoplastic disorder characterized by hypophosphatemia resulting from tumor-secreted fibroblast growth factor-23 (FGF23)." (PMID 37554164, 2023). "Scoliosis and diffusely decreased bone density were revealed by X-ray, while decreased serum phosphate level, and increased BALP and FGF23 levels were detected in the mother, supporting the same diagnosis of hypophosphatemia as her son." (PMID 37278761, 2023). "In the setting of hypophosphatemia, serum FGF23 can be measured to differentiate between FGF23‐mediated and non‐FGF23‐mediated renal phosphate wasting." (PMID 37808399, 2023). "Burosumab addresses the systemic hypophosphatemia mediated by FGF-23, but the osteopontin-mediated local hypomineralization defect has not yet been targeted." (PMID 38137614, 2023). "Some patients have persistent hypophosphatemia and elevated FGF23 levels after resection and need to be monitored." (PMID 36511653, 2023).
hypophosphatemia (continued). "In this respect, osteocytes are one of the primary regulators of systemic phosphate levels through Dmp1 and fibroblast growth factor 23 (FGF23); as in Dmp1 knockout osteocytes, FGF23 is released into the circulation, causing hypophosphatemia." (PMID 37293482, 2023). "Two days after the removal of the tumor, the patient serum FGF23 level was back to normal and hypophosphatemia was corrected." (PMID 37417620, 2023). "Our findings strongly support the notion that hypophosphatemia and rickets in CSHS is due to excessive release of FGF23 by mutation-bearing bone lesions." (PMID 36943390, 2023). "Mineralization defects in the teeth of Hyp-mice seemed to be persistent even when hypophosphatemia was corrected and FGF23 was ablated." (PMID 38137614, 2023). "Autosomal recessive hypophosphatemic rickets type 1 (ARHR1: OMIM #241,520) is also a member of inherited FGF23-related hypophosphatemia." (PMID 37530996, 2023). "Management of FGF23-related hypophosphatemia is with oral phosphate supplements and active vitamin D analogues, alfacalcidol or calcitriol." (PMID 37074534, 2023). "X-linked hypophosphatemia (XLH) is a rare disease of elevated fibroblast growth factor 23 (FGF23) production that leads to hypophosphatemia and impaired mineralization of bone and teeth." (PMID 37813865, 2023). "When these patients were added to the FGF23-related hypophosphatemia group, the specificity improved to 90%." (PMID 35665817, 2023). "Bone HRASG12V mice displayed a marked elevation of plasma-intact FGF23, phosphaturia, hypophosphatemia, and osteomalacia." (PMID 36943390, 2023). "In accordance with previous studies, DMP1 deficiency in Dmp1KO mice increased serum cFGF23, iFGF23, and i/c FGF23 levels, which led to increased FePi, resulting in hypophosphatemia." (PMID 37943605, 2023). "More recently, Lin and Ganda reported a more typical case of tumor-induced osteomalacia with elevated FGF-23 and significant hypophosphatemia." (PMID 37342302, 2023). "FAM20C mutations were identified during whole-exome sequencing in patients with FGF23-related hypophosphatemia, dental anomalies, and ectopic calcification." (PMID 36776964, 2023). "In the Dmp1-null mouse model of ARHR, genetic overexpression of a Dmp1 transgene fully rescues FGF23 levels, hypophosphatemia, and bone defects, but studies specifically targeting FGF23 in models of ARHR are scarce." (PMID 37943605, 2023). "In contrast, lower extracellular phosphate concentrations lead to FGF23 downregulation, resulting in increased renal phosphate reabsorption and intestinal absorption, counteracting hypophosphatemia." (PMID 37635983, 2023). "The mechanism by which hypophosphatemia occurs is related to a poorly understood dysfunction in the mechanisms of FGF23 degradation." (PMID 37048797, 2023). "Non-FGF23-related hypophosphatemia is managed with oral phosphate alone; active vitamin D analogues are contraindicated in these conditions." (PMID 37074534, 2023). "In conclusion, FGF23-induced hypophosphatemia is only partially responsible for the bone defects observed in Dmp1KO mice." (PMID 37943605, 2023). "Previous studies have shown that dietary Pi supplementation improves bone growth and mineralization in 3- to 7-week-old Dmp1-null mice and that anti-FGF23 antibodies correct hypophosphatemia and bone mineralization in 1- to 4-week-old Dmp1-null mice." (PMID 37943605, 2023). "Other observations casting doubt on skin lesions as the FGF23 source are that the vast majority of patients with congenital nevi do not have hypophosphatemia and that patients with FGF23-mediated hypophosphatemia have concomitant dysplastic bone lesions." (PMID 36943390, 2023). "In the present study, we show that genetic deletion of Fgf23 restricted to mature osteoblasts and osteocytes in mice with ARHR led to a partial correction of FGF23 levels, which was sufficient to fully correct hypophosphatemia." (PMID 37943605, 2023).